GIMAP2 (GTPase, IMAP family member 2)
Description:
The heterodimer formed by GIMAP2 and GIMAP7 has GTPase activity. In contrast, GIMAP2 has no GTPase activity by itself.
Synonyms: hIMAP2; IMAP2; DKFZp586D0824; IAN12
Tractability: Small molecule: a structure with a bound ligand is known; it has a high-quality binding pocket. PROTAC: ubiquitination databases record sites on it; its protein half-life has been measured.
Gene: Protein-coding gene on chromosome 7 (150,685,697 to 150,693,641, forward strand). Ensembl gene ENSG00000106560.
Subcellular location: Lipid droplet
Subcellular location (Human Protein Atlas): Lipid droplets; Nucleoplasm
Gene Ontology:
Molecular function: identical protein binding; protein binding; GTPase activity; GTP binding
Cellular component: lipid droplet; endoplasmic reticulum
Genetic constraint (gnomAD): Loss-of-function variants: 22 observed, 26.41 expected, observed/expected ratio (o/e) 0.83, 90% interval 0.59 to 1.19. The upper end of that interval is the gene's LOEUF score, 1.19, which puts it in group 5 of 6, group 1 being the genes least tolerant of losing a copy. Missense variants: 391 observed, 386.42 expected, observed/expected ratio (o/e) 1.01, 90% interval 0.93 to 1.1. Synonymous variants: 158 observed, 143.14 expected, observed/expected ratio (o/e) 1.1, 90% interval 0.97 to 1.26.
Homologues: Orthologues: chimpanzee GIMAP2 (99% identical), macaque GIMAP2 (93% identical), rabbit GIMAP2 (71% identical), dog GIMAP2 (67% identical), pig GIMAP2 (64% identical). Paralogues in human: GIMAP5 (34% identical), GIMAP1 (34% identical), GIMAP4 (30% identical), GIMAP6 (29% identical), GIMAP8 (28% identical), GIMAP7 (26% identical), GIMD1 (14% identical).
Diseases named in the same sentence as GIMAP2 in open-access papers:
GIMAP2 is named in the same sentence as 13 diseases in open-access papers, as found by Europe PMC text mining. Sharing a sentence is not in itself a finding about the gene and the disease. The quoted sentences say what the papers report.
lung carcinoma (2 papers, 2020 to 2021). "GIMAP1/4/6/7/8 were predicted to have a higher association with LUAD filtered by RNA expression in this study, while GIMAP2 was predicted to have an association with lung carcinoma and GIMAP2 was predicted to have an association with sepsis." (PMID 33115964, 2020). "The survival analysis of the GIMAP family was performed, and the results showed that high levels of GIMAP1, GIMAP2, GIMAP4, GIMAP5, GIMAP, GIMAP7 and GIMAP8 mRNA expression levels were associated with better overall survival of patients with lung cancer." (PMID 34604035, 2021).
anaplastic large cell lymphoma (1 paper, 2021). Anaplastic large cell lymphoma (ALCL) is a rare and aggressive peripheral T-cell non-Hodgkin lymphoma, belonging to the group of CD30-positive lymphoproliferative disorders, which affects lymph nodes and extranodal sites. "The expression of GIMAP5 occurs in many T cell leukemic cell lines and in anaplastic large cell lymphoma (ALCL) cell lines while the expression of GIMAP1, GIMAP2, GIMAP6 and GIMAP7 were down-regulated in ALCLs." (PMID 34135906, 2021).
large cell lung carcinoma (1 paper, 2020). "However, GIMAP2 was found in the large cell lung carcinoma not in the LUAD with lower mRNA expression." (PMID 33115964, 2020).
lentivirus infection (1 paper, 2021). Virus diseases caused by the Lentivirus genus. "Moreover, targeted analyses of the SSC5D, GIMAP2, and GPR37 genes indicate links between immune system elements and lentivirus infection." (PMID 33810360, 2021).
liver fibrosis (1 paper, 2021). "Studies on the gene expression profile of HCV (Hepatitis C Virus)-infected liver fibrosis in humans found GIMAP2 to be upregulated in the early stage of the disease as compared to the later stages." (PMID 33810360, 2021).
oral squamous cell carcinoma (1 paper, 2024). "Abnormal GIMAP2 expression affects the progression of oral squamous cell carcinoma by promoting the cell cycle and inhibiting cell apoptosis." (PMID 38789729, 2024).
sarcoma (1 paper, 2020). A usually aggressive malignant neoplasm of the soft tissue or bone. "After performing validation in both TCGA dataset and GEO dataset GSE17679, we extracted a group of immune-related genes, including NR1H3, VAMP5, GIMAP2, GBP2, HLA-E and CRIP1 that were most significant to predict good outcomes in sarcoma patients." (PMID 33316779, 2020).
infection (2 papers, 2019 to 2021). The state of being infected such as from the introduction of a foreign agent such as serum, vaccine, antigenic substance or organism. "In turn, GIMAP2 plays a crucial role in lymphocyte maturation at the early stage of infection." (PMID 33810360, 2021). "In addition, a number of genes associated with GTPase activities, which included GIMAP2, RACGAP1, AGBL5 and RAP1GDS1, were down-regulated during the early phase of infection." (PMID 30789917, 2019).
GIMAP2 also shares sentences with these, for which no sentence is quoted: cancer (2 papers); tumor (2); leukemia (1); lymphoma (1); Sepsis (1).